TLR9 (toll like receptor 9)
Diseases named in the same sentence as TLR9 in open-access papers (continued):
Sharing a sentence is not in itself a finding about the gene and the disease.
cancer (continued). "TLR9 rs187084, a UTR-SNP which probably interferes with transcription factors binding, has been shown to modify susceptibility to diseases specially renal transplant recipients and cancers." (PMID 27478803, 2016). "Combination therapy with TLR9 agonist and radiation is a promising strategy of cancer treatment." (PMID 27336891, 2016). "Thus, combination of emulsion type adjuvant and a TLR9 agonist is a potent formulation for peptide-based therapeutic vaccines for cancer therapy." (PMID 26621839, 2016). "TLR9 regulates expression of genes critical for function of non-malignant immune cells but the TLR9 downstream gene targets in cancer cells are mostly unknown." (PMID 26046794, 2015). "Little is known about downstream effects of TLR9 signaling in human cancer cells." (PMID 26046794, 2015). "It has been reported that TLR9 signaling could directly promote cancer cell invasion via, at least in part, AP-1 (jun proto-oncogene) activated MMP-2 secretion in HB cells." (PMID 26087186, 2015). "Therefore, the activation of inflammasomes by our X-DNA in dendritic cells offers an additional advantage for anti-cancer therapy compared with a single activator for TLR9." (PMID 25971982, 2015). "Principal clinical trials investigating TLR-9 agonists for cancer treatment." (PMID 28548068, 2014). "In the past few years, we studied these aspects and contributed to clarifying several novel mechanisms of IMOs and, more in general, of TLR-9 agonists, demonstrating that their antitumor activity is attributable also to their direct effects on cancer cell behavior." (PMID 28548068, 2014). "If this is the case, then patients with low-TLR9–TNBC tumors might benefit from anti-cancer immune therapy." (PMID 25101078, 2014). "Despite the well-documented expression of TLR9 in various cancers and invasive response to TLR9 ligands in vitro, the involvement of this protein in cancer pathophysiology remains unclear." (PMID 24959259, 2014). "In principle, however, such DNA-induced and TLR9-mediated cancer cell invasion could represent a novel mechanism of treatment resistance." (PMID 25101078, 2014). "The regulation of TLR9 expression, as well as the possible physiological ligands which may induce invasion in TLR9-expressing cancer cells, also remain poorly characterized." (PMID 24959259, 2014). "Whether self-DNA-induced and TLR9-mediated cancer cell invasion takes place in vivo in breast or any cancer is currently unknown." (PMID 25101078, 2014). "Furthermore, since the procedures of the current study were performed without the addition of exogenous ligands, the results additionally suggest that TLR9 expression is sufficient to control cancer cell invasion." (PMID 24959259, 2014). "Subsequent reports suggested that TLR9 directly promoted cancer cell invasion." (PMID 25309546, 2014). "The prognostic significance of TLR9 in cancers appears to be bimodal." (PMID 25101078, 2014). "The expression of functional active TLR9 in human malignant tumors might affect treatment approaches using CpG-ODN." (PMID 24161202, 2013). "Hypoxia is another important regulator of TLR9 expression in cancer." (PMID 23761830, 2013). "Stimulation of TLR9 by synthetic DNA ligands or bacterial DNA also stimulates cancer cell invasion." (PMID 23761830, 2013). "Notably, the present study revealed that chloroquine treatment upregulates TLR9 mRNA expression in cancer cells." (PMID 24273604, 2013). "Therefore, the impact of TLR9 expression in tumors on the prognosis of a patient appears to be dependent on the type of cancer." (PMID 23761830, 2013). "TLR9 -1486C was also identified as an independent marker of poor survival of carcinoma." (PMID 23776537, 2013). "TLR9 agonists stimulated the secretion of IgM in human epithelial cancer cells." (PMID 23251529, 2012).
cancer (continued). "Combination therapy with TLR9 agonist and RT induces systemic anti-tumoral humoral response, augments tumoral infiltration of NKDCs, reduces pulmonary metastases and improves survival in a murine model of 3LL cancer." (PMID 22666458, 2012). "Thus TLR9 agonists are considered as an adjuvant treatment for cancer patients that can be combined with traditional local therapies, such as, RT." (PMID 22666458, 2012). "CpG is synthetic ODN with unmethylated CG dinucleotides within particular sequence contexts, CpG ODN has been used in clinical trials as a vaccine adjuvant for immunotherapy of cancer since it can mimic microbial DNA and activate immune system through the binding of TLR9." (PMID 20696081, 2010). "In PBMCs of HBV-infected patients, TLR7 expression and TLR9 mRNA are down-regulated, but TLR9 shows increased protein expression, which may play important roles in cancer cells." (PMID 21078198, 2010). "Moreover, in mice, positive effects of dual CD40 and TLR activation have been well-described, providing further pre-clinical rationale to test CD40/TLR9 combined therapy in human cancer patients." (PMID 19906293, 2009). "In order to characterize possible interactions between malignant cells and CpG-ODN, we investigated whether TLR9 is present in malignant tumors." (PMID 15631627, 2005). "We conclude the expression of a functionally active TLR9 in human malignant tumors." (PMID 15631627, 2005). "However, previous studies focused on the role of TLR9 pathway in cancer cells." (PMID 40038250, 2025). "However, most studies have shown that TLR9 agonists are promising therapeutic agents for cancer." (PMID 38685971, 2024). "Of interest, recent evidence pinpoints a synergistic function of TLR9 and Notch1 in driving the metabolic adaptation for populating cancer stem-like cells, indicating that ALD-DNA-induced TLR9 and Notch1 signaling might drive metabolic adaptation in macrophages." (PMID 37626904, 2023). "The role of TLR9 in MDSCs is also controversial and may be relevant to cancer types." (PMID 36911674, 2023). "Discovering pathways originating from the cell surface TLR9 may uncover new functions of endosomal TLR9, enhance our comprehension of the triggering of inflammation or cancer diseases, and potentially expose previously unknown specific ligands for the sTLR9 receptor." (PMID 37724102, 2023). "Similarly, TLR9 has antitumor properties, but inappropriate activation of TLR9 during chronic inflammation may lead to the activation of transcription factors that induce pro-cancer activity." (PMID 36365103, 2022). "Upregulation in TLR9 transcription could be functional to clear viral and bacterial infection(s) but, paradoxically, TLR9 overexpression was previously linked to HPV persistence, high-grade lesions, and cancer." (PMID 36422611, 2022). "The exact molecular mechanism of TLR9 signalling inhibition in cancer cells remains unknown." (PMID 32715647, 2020). "This hypothesis is additionally sustained by the fact that TLR9 is upregulated in cancer tissue." (PMID 30863783, 2019). "Importantly, in cancer patients, TLR9 expression is not limited to plasmacytoid DCs and B cells as in healthy subjects but is upregulated in PMN-MDSCs, which are the dominant tolerogenic cell population accumulating in the blood of patients with various cancers." (PMID 29921770, 2018). "Additionally, human TLR9 occurs at 3p21.3, a region frequently deleted in human cancers." (PMID 29883450, 2018). "However, the mechanism of the role of TLR9 in the development of cancer remains to be elucidated." (PMID 29263932, 2017). "Thus, the increased sensitivity could actually indicate that BPs promote cancer cell growth via TLR9." (PMID 27888633, 2016). "However, some reports showed also opposite effects of TLR-9 agonists in other cancer settings." (PMID 28548068, 2014). "However, if true, it would mean that patients with low-TLR9–TNBC could especially benefit from adjuvant cancer immunotherapy." (PMID 25101078, 2014).
cancer (continued). "Nevertheless, the facts that TLR9 agonists increases IgM secretion from cancer cells and that this increase can be abolished by chloroquine and MyD88 knockdown with siRNA suggest that the expression and secretion of cancer-derived IgM is mediated through the TLR9-MyD88 pathway." (PMID 23251529, 2012). "We previously engineered a cancer therapeutic vaccine platform, μGCVax, by co-loading tumor antigen peptides, STING and TLR9 agonists into porous silicon microparticles." (PMID 42042292, 2026). "Nucleotide- or deoxynucleotide-based adjuvants (unmethylated CpG deoxynucleotides [CpG ODN]24–26, a TLR9 agonist, and polyincosinic-polycytidylic acid [Poly I:C]27, 28, a TLR3 agonist ) are currently used for cancer immunotherapy." (PMID 40832663, 2025). "Class A CpG-oligonucleotides (ODNs), a Toll-like receptor 9 (TLR9) agonist, have been applied for treating inflammatory diseases and cancer in preclinical studies and clinical trials." (PMID 40337520, 2025). "Toll-like receptor 9 (TLR9), a member of the TLR family, has shown great potential as a target for the treatment of cancer, with plasmacytoid dendritic cells (pDCs), constitutively expressing TLR9 being the primary target." (PMID 40317310, 2025). "Toll-like receptor 9 (TLR9) agonists have been widely studied in both monotherapy and combination therapy for cancer treatment." (PMID 41425253, 2025). "These make class A ODN an attractive candidate for targeting the TLR9 signaling in FRC to control inflammatory responses during inflammation and cancers." (PMID 40337520, 2025). "Necrotic cancer cells release cfDNA, which increases CRC cell survival by stimulating TLR9 signaling." (PMID 38685971, 2024). "For example, TLR9 agonists, such as CpG-ODN, activate dendritic cells and macrophages, stimulating T lymphocytes for anti-cancer activity." (PMID 39451226, 2024). "In vivo studies demonstrated that CTSK plays an key role in the gene induction program regulated by TLR9 signaling, and CTSK-dependent TLR9 signaling in DCs contributes to cancer metastasis and autoimmune inflammation." (PMID 37935734, 2023). "Considering the intracellular TLRs, TLR9 expression was detected in the TME after radiotherapy and this finding suggests the beginning of the cancer recurrence process." (PMID 37822929, 2023). "As a Toll-like receptor-9 (TLR9) agonist, CpG-ODN is known to induce anti-cancer immune responses and exert direct effects against cancer cells, serving as a cancer therapeutic agent." (PMID 36678249, 2023). "In particular, Toll-like receptor 9 (TLR-9) has emerged as a focal point in the crossroads of immunomodulation and cancer development." (PMID 37894471, 2023). "TLR1, TLR2, TLR3, TLR4, and TLR5 expression levels were high across the six immune subtypes in the pan-cancer data; TLR6, TLR7, TLR8, and TLR10 expression levels were moderate; and TLR9, TLR12P, and TLR8-AS1 expression levels were extremely low." (PMID 35801728, 2022). "TLR agonists approved by the FDA for the treatment in cancer patients include Bacillus Calmette-Guérin (BCG) (activates TLR2, TLR3, TLR4 and TLR9), monophosphoryl lipid (MPL) (TLR4 agonist) and imiquimod (TLR7 agonist)." (PMID 36365103, 2022). "NETs also activate a series of TLR9-dependent signaling pathways, such as the MAP kinase pathway and NF-κB pathway, in cancer cells by releasing high mobility group box 1 (HMGB1), thus promoting cell proliferation, adhesion, migration, and invasion." (PMID 36365233, 2022). "Pre-clinical testing, and data from cancer treatment trials, demonstrates that MGN1703 activates immune functions through the TLR9 pathway." (PMID 35865810, 2022). "We confirmed the expression of TLR9 and related endosomal protein TLR7 in the LM samples at protein and transcript levels on the tissues obtained from seven different cancer patients." (PMID 35697801, 2022).
cancer (continued). "Furthermore, DNA from chemotherapy-killed cancer cells could transfect living cancer cells and mediate invasion via TLR9, whereas TLR9 affected response to pharmacotherapy by a TLR9-mediated inflammation, as shown in a mice BC model bearing tumors overexpressing TLR9." (PMID 33578793, 2021). "TLR2, TLR4, TLR9, and RAGE have been identified as the most common receptors for HMGB1 on cell surface in different cancer models and patients." (PMID 33614649, 2021). "Agonists of innate immune pathways including TLR9 and STING should be considered to activate DCs and originate effective priming of T cells to steer forward through the cancer-immunity cycle." (PMID 35008305, 2021). "Trials containing IO agents other than PD-L1/PD-1 inhibitors without chemotherapy included agents targeting IL-10 inhibitor, toll-like receptor 9 (TLR9) agonist and cancer vaccines." (PMID 33816286, 2021). "In both of these reports, the authors have shown that TLR9 participates in CSCs formation via STAT3, a multi-functional signal transduction molecule widely involved in stemness and cancer." (PMID 32843056, 2020). "The investigation of molecular pathways shows that NOB is able to inhibit TLR9/IRF7 and TLR4/TRIF/IRF3 in suppressing the proliferation and growth of cancer cells." (PMID 32380783, 2020). "TLR9 promotes survivability of cancer cells by activating the TLR9—MyD88 –NF-kB signaling pathway, whereas AIM2 induces apoptosis in cancer cells being a part of the inflammasome." (PMID 31205871, 2019). "ROS generation, DNA damage, cell cycle, expression of TLR9, AIM2, NF-kB, STAT3, and RNA for 44 genes affecting the cancer cell viability were evaluated." (PMID 31205871, 2019). "Recently, an in situ vaccination was used to trigger a T cell immune response to attack cancer cells (e.g., the combination of a Toll-like receptor 9 (TLR) ligand and an anti-OX40 antibody can successfully cure various types of cancer)." (PMID 30011807, 2018). "This synthetic, short, single‐stranded oligonucleotide activates Th1 responses via interaction with TLR9, and due to inhibition of Th2 responses by Th1 cytokines, including IFN‐γ and IL‐12; this motif is useful in cancer immunotherapy." (PMID 28944998, 2018). "Specifically, we engineered MFs to be assembled of synergistic CpG and Stat3-silencing shRNA, such that TLR9 and STAT3 signaling pathways were synergistically leveraged to elicit potent immunostimulation in APCs for cancer immunotherapy." (PMID 29133898, 2017). "In BxPC-3 and MIAPaCa-2 cancer cells TLR2 and -9 expression clearly dominated (BxPC-3: TLR2 42.9%, TLR4 2.9%, and TLR9 43.8%; MIAPaCa-2 TLR2: 40.2%, TLR4 8.5%, and TLR9 88.5%) (top and center)." (PMID 27941651, 2016). "As shown by this study, TLR9/NF-κB/STAT3 signaling coordinates expression of genes related to differentiation and renewal of normal or cancer stem cells." (PMID 26046794, 2015). "As suggested by both our transcriptome and protein analyses, the link between TLR9/NF-κB and STAT3 signaling likely relies on IL-6 secretion by cancer cells." (PMID 26046794, 2015). "This is a result of the concerted expression of genes related to cancer stem cell maintenance through NF-κB/RELA and STAT3 as downstream mediators of TLR9 signaling." (PMID 26046794, 2015). "Whereas TLR-9 agonists reduced the expression of RAD51, silent mating type information regulation 2homolog (SIRT)-1, RAD54B and RAD23B in cancer cells, the same genes were up-regulated in immune cells." (PMID 28548068, 2014). "We found that CpG 2006, the most common TLR9 agonist, significantly increased secretion of IgM along with upregulated phosphorylation of ERK and IkB in the human epithelial cancer cells, similar to B cells." (PMID 23251529, 2012). "Due to its strong immune stimulatory effects through TLR9, CpG-containing oligodeoxynucleotides (CpG ODN) have been tested in multiple clinical trials as vaccine adjuvant for infectious diseases and cancer." (PMID 22470514, 2012).
cancer (continued). "Samples of carcinomas with recurrence exhibited a significant increase in the mRNA levels of TLR3, TLR4 and TLR9." (PMID 21129170, 2010). "In both studies, CpG-ODN stimulation did not alter cellular proliferation, indicating that TLR9 signaling primarily promotes cancer progression and metastatic potential." (PMID 41601666, 2026). "TLR9 is primarily expressed in antigen-presenting cells, although its expression has also been found in some nonimmune and cancer cells." (PMID 38201300, 2024). "Furthermore, significant correlations were found between high TLR9 expression and poor prognosis, invasion, metastasis, and TNM staging of cancers." (PMID 38685971, 2024). "Likewise, the TLR9 agonist unmethylated oligonucleotide CpG, which is recognized as a bacterial DNA by TLR9, increases MMP-13 expression and activity, reduces TIMP-3 synthesis and the invasion capacity of breast MDA-MB-231 cancer cells." (PMID 38069210, 2023). "To overcome these limitations, we previously developed a strategy to deliver oligonucleotide-based STAT3 inhibitors, such as antisense oligonucleotides (ASOs), specifically into Toll-like receptor-9 (TLR9) expressing myeloid cells, B cells, and certain cancer cells." (PMID 38259453, 2023). "K3-SPG, a second-generation nanoparticulate Toll-like receptor 9 (TLR9) ligand consisting of K-type CpG oligodeoxynucleotide (ODN) wrapped with SPG (schizophyllan), integrates the best of conventional CpG ODNs, making it an ideal cancer immunotherapy adjuvant." (PMID 35136110, 2022). "For instance, whereas the expression trend in LUAD was generally identical to that in pan-cancer, TLR9 was not differentially expressed amongst any of the six immunological subtypes." (PMID 35801728, 2022). "TLR9 represents an intracellular PRR, which is predominantly expressed in the cytoplasm of macrophages, dendritic cells and specific antigen-presenting cells as well as cancer cells." (PMID 35239059, 2022). "Additionally, TLR6, TLR7, TLR8, TLR9, and TLR10 expression was up- or down-regulated in different cancer species." (PMID 35801728, 2022). "TLR9 stimulation also induces the activation of natural killer cells, T cells, B cells, and pDCs, thereby enhancing pro-inflammatory and T Helper 1 (Th1) cytokines such as IL12 stimulation and CTL cytotoxicity capable of eliminating viral pathogens and cancer." (PMID 36611945, 2022). "The attraction of immune cells by stimulation of TLR9 also looks like an innovative but still not fully described way of weakening emerging anti-cancer immunity." (PMID 36230984, 2022). "The interrelated role of HGFR inhibition and TLR9/autophagy signaling in HT29 cancer cells subjected to modified self-DNA treatments has not been clarified." (PMID 35551547, 2022). "Likewise, a bi-adjuvant neoantigen nanovaccine (banNV) was developed for potent cancer immunotherapy by co-delivering a peptide neoantigen (Adpgk) with two adjuvants (TLR 7/8 agonist R848 and TLR9 agonist CpG)." (PMID 35745800, 2022). "The interrelated roles of IGF1R inhibition and TLR9/autophagy signaling in HT29 cancer cells have not yet been clarified." (PMID 35651701, 2022). "Among these agonists, CpG ODN is a TLR-9 agonist that was employed as mono or combined immunotherapy with conventional chemotherapy and other therapies in multiple human clinical trials, phases II and III, against several types of cancer." (PMID 34202080, 2021). "In the present study, we found that the mtDNA-STING pathway was important for the protective antitumor effect of an irradiated cancer cell vaccine, while TLR9 and IL-1β signaling was not." (PMID 32398808, 2021). "However, the literature investigating the relationships between TLR9 level, EBV infection and cytokine production in cancer is scarce." (PMID 34439137, 2021). "Suppression of PKD in myeloid cells prevents pro-inflammatory cytokine expression in response to TLR9 agonists and bacterial infection, but the effects in response to cancer are not known." (PMID 35046933, 2021).